VIP (vasoactive intestinal peptide)
Diseases named in the same sentence as VIP in open-access papers (continued):
Sharing a sentence is not in itself a finding about the gene and the disease.
amnesia (1 paper, 2020). Pathologic partial or complete loss of the ability to recall past experiences ( AMNESIA, RETROGRADE) or to form new memories ( AMNESIA, ANTEROGRADE). "Similar anti-amnesic effects of VIP were reported by Glowa and colleagues, demonstrating that ICV infusion of VIP ameliorated the amnesia induced by gp120 (external envelope glycoprotein of the human immunodeficiency virus) in Morris water maze test." (PMID 32785144, 2020). "In contrast, intraperitoneal, subcutaneous, or ICV injection of VIP improved the scopoloamine-induced amnesia of rats." (PMID 32785144, 2020).
aneurysm (1 paper, 2022). Bulging or ballooning in an area of an artery secondary to arterial wall weakening. "The ViP signature effectively subclassified acute KD patients with giant aneurysms (CAA-giant) from to those with either no aneurysms (CAA−; p value = 0.0027) or small aneurysms (CAA-small; p value = 0.0013)." (PMID 35577777, 2022).
ankylosing spondylitis (1 paper, 2022). An autoimmune chronic inflammatory disorder characterized by inflammation in the vertebral joints of the spine and sacroiliac joints. "Moreover, another study described higher levels of serum VIP in ankylosing spondylitis patients compared to healthy donors and reported a significant association with platelet count." (PMID 35955723, 2022).
Anorexia (1 paper, 2015). Lack of desire to eat (loss of appetite). "In the case of stress‐induced anorexia, increased POMC may contribute to this inhibitory role, whereas, for incubation, reduced feeding may also be associated with increased expression in the hypothalamus of the anorexigenic peptide vasoactive intestinal peptide." (PMID 26017156, 2015).
Aqueductal stenosis (1 paper, 2011). Stenosis of the cerebral aqueduct (also known as the mesencephalic duct, aqueductus mesencephali, or aqueduct of Sylvius), which connects the third cerebral ventricle in the diencephalon to the fourth ventricle, which is between the pons and cerebellum. "The same findings were reported for other proteins (neurofilament light protein, tau, sulfatide, vasoactive intestinal peptide and neuropeptide Y) in case of iNPH and aqueductal stenosis." (PMID 21569454, 2011).
Arrhythmia (1 paper, 2016). Any cardiac rhythm other than the normal sinus rhythm. "Second, lack of VIP signalling caused by gene-targeted disruption of either Vip or its cognate receptor Vpac2 leads to an array of disturbed circadian rhythms that range from low amplitude associated with short period length to arrhythmia in the mouse." (PMID 27458725, 2016).
autonomic dysfunction (1 paper, 2025). "Immunofluorescence staining revealed that autonomic dysfunction in AR mice was ameliorated by minocycline, as evidenced by the up-regulation of TH and NPY and down-regulation of ChAT and VIP in the nasal mucosa." (PMID 41019284, 2025). "Immunofluorescence staining revealed that autonomic dysfunction in AR mice was ameliorated by IL-4 NAb, as evidenced by the up-regulation of TH and NPY and down-regulation of ChAT and VIP in the nose." (PMID 41019284, 2025).
bacterial pneumonia (1 paper, 2024). Acute infection of the lung parenchyma caused by bacteria (e.g., Streptococcus pneumoniae, Haemophilus influenzae, Chlamydia pneumoniae, Mycoplasma pneumoniae, and Legionella pneumophila). "In the current study, besides elevated levels of CGRP, SP, VIP, NPY, and PCT peptides in bacterial pneumonia compared to controls, these were also all higher in bacterial pneumonia than in viral pneumonia." (PMID 38183438, 2024). "We found that VIP levels were increased in pediatric patients with bacterial pneumonia, but not in patients with viral pneumonia, compared to healthy controls." (PMID 38183438, 2024). "This may be a sign that VIP may come into prominence in bacterial pneumonia rather than viral pneumonia." (PMID 38183438, 2024).
celiac disease (1 paper, 2019). An autoimmune genetic disorder with an unknown pattern of inheritance that primarily affects the digestive tract. "Moreover, the similar gut microbiota changes seen in the present study compared to inflammatory disorders like Crohn’s and Celiac disease further support a common inflammatory tone within the GITs of VIP KO mice." (PMID 31849864, 2019).
Cholecystitis (1 paper, 2015). The presence of inflammatory changes in the gallbladder. "Gallbladder nociceptors also release substance P and vasoactive intestinal peptide to induce a neurogenic inflammatory environment which appears to be a prominent contributor to cholecystitis development." (PMID 26689256, 2015).
chronic bronchitis (1 paper, 2018). A type of chronic obstructive pulmonary disease characterized by chronic inflammation in the bronchial tree that results in edema, mucus production, obstruction, and reduced airflow to and from the lung alveoli. "However, an argument for causal relationship might be inferred from studies demonstrating that chronic bronchitis, which is a common feature of COPD, is associated with increased VIP innervation to the mucus glands." (PMID 30081920, 2018). "However, receptors for VIP (vasoactive intestinal peptide receptor 1 (VPAC), vasoactive intestinal peptide receptor 2 (VPAC2)) were elevated in the epithelium and glands in biopsies from smokers with chronic bronchitis." (PMID 30081920, 2018).
colon adenocarcinoma (1 paper, 2023). "In clinical studies, radiolabeled-VIP binds VPAC and detects primary and metastatic tumors in a variety of cancer histologies, and serum VIP levels are > two-fold higher in patients with colon adenocarcinoma." (PMID 37444395, 2023).
colonic pseudo-obstruction (1 paper, 2021). Functional obstruction of the COLON leading to MEGACOLON in the absence of obvious COLONIC DISEASES or mechanical obstruction. "In cases of VIPoma and colonic pseudo-obstruction, which cause marked watery diarrhea, K secretion into the stool is abnormally high, suggesting the involvement of vasoactive intestinal peptide (VIP) in intestinal K regulation." (PMID 34063969, 2021).
cystic ovaries (1 paper, 2014). "The present experiment revealed that the distribution and density of nerve fibres containing VAChT, nNOS, VIP and/or SOM have changed in the gilt cystic ovaries, induced by DXM treatment on days 7–21 of the estrous cycle." (PMID 24519145, 2014).
diabetic retinopathy (1 paper, 2019). "In a retinal disease such as diabetic retinopathy, VIP may contribute to the protection of retinal neurons by reducing outer BRB dysfunction, probably through an inhibition of VEGF and of hypoxia-inducible factor 1α (HIF1-α), the main transcriptional regulator of VEGF expression." (PMID 31374938, 2019).
distal colitis (1 paper, 2017). Particular variety of ulcerative colitis where only the left half of the colon is inflamed. "Active inflammatory sites of patients with distal colitis had lower VIP compared to healthy tissue samples of distal colitis." (PMID 29232715, 2017). "Samples from patients with distal colitis and pancolitis had lower neuronal and non-neuronal VIP when compared with the control group." (PMID 29232715, 2017). "Healthy controls and healthy tissue samples of distal colitis had similar levels of neuronal and non-neuronal VIP." (PMID 29232715, 2017).
Down syndrome (1 paper, 2024). "VIP and VPAC1 receptors are upregulated in mouse models of Down syndrome, a disease associated with excessive GABAergic inhibition, which also displays impaired synaptic plasticity specifically in TBS but not high-frequency stimulation-induced LTP in vitro." (PMID 38540797, 2024).
Dysphagia (1 paper, 2024). "We examined the induced blood VIP protein levels and esophageal biopsy mRNA levels of VIP and VIP receptors (VACP1 and CRTH) in dysphagia patients compared to normal individuals (normal vs. EoE, p < 0.001, n = 14–18)." (PMID 38391908, 2024).
enteritis (1 paper, 2025). Inflammation of the small intestine. "The gastrointestinal regulatory peptides that are primarily associated with enteritis include SP, ET‐1, SS, and VIP." (PMID 39803293, 2025). "Gastrointestinal regulatory peptides related to enteritis include substance P (SP), endothelin (ET‐1), somatostatin (SS), and vasoactive intestinal peptide (VIP)." (PMID 39803293, 2025).
enteropathies (1 paper, 2020). "One of the neuronal substances that are widely distributed in the intestinal innervations, and which may be involved in mechanisms connected with enteropathies, is vasoactive intestinal polypeptide (VIP)." (PMID 32998326, 2020).
epileptic seizures (1 paper, 2024). "Initially, various types of GABAergic neurons, including parvalbumin (PV), somatostatin (SST), and vasoactive intestinal peptide (VIP) neurons, are employed in epileptic seizures, followed by glutamatergic neurons." (PMID 40217549, 2024).
erectile dysfunction (1 paper, 2020). Persistent or recurrent inability to achieve or to maintain an erection during sexual activity. "Aviptadil, a combination of synthetic vasoactive intestinal polypeptide (VIP) (~28 amino acids) and phentolamine, is approved in Europe for the treatment of erectile dysfunction." (PMID 32784499, 2020).
esophageal adenocarcinoma (1 paper, 2023). A malignant tumor with glandular differentiation arising predominantly from Barrett mucosa in the lower third of the esophagus. "Interestingly, the cell line expression data did not recapitulate the VIP and ZEB1 associations seen in healthy and cancer tissues and showed only a statistically significant association between VIP and ZEB1 in a limited number of esophageal adenocarcinoma cases (p = 0.05)." (PMID 37444395, 2023).
esophageal cancer (1 paper, 2023). A primary or metastatic malignant neoplasm involving the esophagus. "VIP and ZEB1 expression were both lower in stomach, colon, and esophageal cancer tissue compared to healthy tissue (p < 0.0001)." (PMID 37444395, 2023).
esophageal motility disorders (1 paper, 2022). "Decreased delivery of postganglionic transmitters—including nitric oxide and vasoactive intestinal peptide—at the level of the esophagogastric junction causes the failure of deglutition-induced LES relaxation in esophageal motility disorders." (PMID 35455706, 2022).
facial paralysis (1 paper, 2025). Severe or complete loss of facial muscle motor function. "Another study confirmed that Taiyang point through Dicang, and Jiache point could play a role in improving facial paralysis by down-regulating by substance P (SP), vasoactive intestinal peptide (VIP), calcitonin gene-related peptide (CGRP)." (PMID 40352774, 2025).
Failure to thrive (1 paper, 2015). Failure to thrive (FTT) refers to a child whose physical growth is substantially below the norm. "The other is the excessive production of vasoactive intestinal peptide (VIP) resulting in watery diarrhoea and failure to thrive." (PMID 25889326, 2015).
food allergy (1 paper, 2025). Gastrointestinal disturbances, skin eruptions, or shock due to allergic reactions to allergens in food. "The administration of OVA/VIP-primed ie-ECs also suppressed experimental food allergy." (PMID 40565252, 2025).
fungal keratitis (1 paper, 2022). "In fungal keratitis, VIP treatment downregulates pro-inflammatory cytokine expression, and this effect can be reversed by a VIP antagonist." (PMID 36009532, 2022).
germ cell tumor (1 paper, 2022). A benign or malignant, gonadal or extragonadal neoplasm that originates from germ cells. "Second-line therapy regimens and above, including VIP and TIP, improve the prognosis of recurrent germ cell tumors." (PMID 36016622, 2022).
glaucoma (1 paper, 2021). Increased pressure in the eyeball due to obstruction of the outflow of aqueous humor. "This study increased our understanding of the regulatory role of VIP in stabilizing the interaction between the actin cytoskeleton and cell junctions and suggests a promising target strategy for glaucoma treatment." (PMID 34552687, 2021). "This study provides insights into the role of VIP in stabilizing the interaction between the actin cytoskeleton and cell junctions and may provide a promising targeted strategy for glaucoma treatment." (PMID 34552687, 2021).
hypersomnia (1 paper, 2025). A sleep disorder characterized by excessive sleepiness. "For hypersomnia, VIP’s high z axis value may relate to VIPomas, where octreotide inhibits excessive VIP secretion." (PMID 39954672, 2025). "However, VIP is produced by neurons in the SCN of the hypothalamus where it maintains normal circadian rhythms, supporting its potential involvement in hypersomnia too." (PMID 39954672, 2025).
hyperthyroidism (1 paper, 2020). Overactivity of the thyroid gland resulting in overproduction of thyroid hormone and increased metabolic rate. "Levels of VIP were normalized in euthyroid GD patients independently of the treatment used to control hyperthyroidism, including antithyroid drugs, radioiodine or surgery." (PMID 32747757, 2020). "Specifically, patients who had not received any prior treatment for hyperthyroidism had the lowest median serum VIP levels (325.08 pg/ml) compared to patients who had received anti-thyroid drugs (345.01 pg/ml, P = 0.006) or radioiodine (361.92 pg/ml, P = 0.024)." (PMID 32747757, 2020).
insomnia (1 paper, 2025). A sleep disorder characterized by difficulty in falling asleep and/or remaining asleep. "Quantitative analysis revealed significant brain-gut peptide dysregulation in insomnia-model rats, with hypothalamic VIP and GH levels reduced compared to controls (p < 0.001)." (PMID 41409981, 2025).
intestinal tumors (1 paper, 2023). "Previous studies have found a significant increase in VIP in mice with intestinal tumors through AOM/DSS induction." (PMID 36890467, 2023).
liver cancer (1 paper, 2020). An epithelial or non-epithelial malignant neoplasm that arises from the liver. "Evidence has already shown that VIP can prevent the development of liver cancer through apoptosis of the cAMP/Bcl-xL pathway, but its prognostic significance in CRC requires further investigation." (PMID 33330631, 2020).
Liver cirrhosis (1 paper, 2021). "Liver cirrhosis increased the risk of AF (HR = 1.46; 95% CI = 1.18–1.80), likely due to cirrhotic cardiomyopathy, vasoactive intestinal peptide, and galectin-3." (PMID 34539379, 2021).
liver steatosis (1 paper, 2024). "Global inhibition of VIP-producing neurons also resulted in a significant reduction in liver steatosis." (PMID 39761015, 2024). "Using both conditional genetic inactivation of VIPR2 in ILC3 and chemogenetic-mediated inhibition of VIP-producing neurons, we found that hepatic steatosis can be attenuated by modulation of VIPergic signaling in innate lymphoid cells." (PMID 39761015, 2024). "We observed a marked reduction in hepatic steatosis following intermittent global inhibition of VIP-producing neurons in mice." (PMID 39761015, 2024). "Intermittent inhibition of VIP-producing neurons for 16 weeks resulted in a striking reduction in liver steatosis, suggesting that global intermittent inhibition of VIP signaling could attenuate MASLD." (PMID 39761015, 2024). "Our observation of attenuated liver steatosis with impaired VIP signaling to ILC3 prompted us to evaluate whether the global modulation of VIP-neurons would be feasible in the setting of MASLD." (PMID 39761015, 2024). "We next evaluated whether VIP-mediated inhibition of IL-22 production by intestinal ILC3 contributes to the liver steatosis phenotype in mice fed HFD." (PMID 39761015, 2024). "This suggests that differences in the composition of the intestinal microbiota associated with the absence of VIP modulation of ILC3 may be associated with the observed liver phenotype from diet-induced hepatic steatosis." (PMID 39761015, 2024). "Specifically, both global inhibition of VIP-producing neurons and the targeted removal of the neuroinhibitory control of ILC3 (namely VIPR2) reduced hepatic steatosis in a preclinical model of MASLD induced by an HFD." (PMID 39761015, 2024). "In conclusion, our findings highlight the potential for targeting VIP signaling and ILC3 as a novel therapeutic strategy to ameliorate hepatic steatosis and highlight the need to further understand how neuroimmune modulation can affect metabolic disorders, including MASLD." (PMID 39761015, 2024).
malaria (1 paper, 2021). Malaria is a serious and sometimes fatal disease caused by a parasite that commonly infects a certain type of mosquito which feeds on humans. "The demonstration here that persistent VIP expression of CIS43 confers protection up to 36 weeks post-AAV administration (wpa) against a single or sequential malaria challenges provides clear evidence for the promise of this approach for sustaining high levels of antibody." (PMID 33332286, 2021).
male infertility (1 paper, 2024). The inability of the male to effect fertilization of an ovum after a specified period of unprotected intercourse. "Exploring the practical implications of PACAP and VIP in diagnosing and treating male infertility can not only advance our understanding of their mechanisms of action but also drive the development of innovative strategies for addressing reproductive health challenges in men." (PMID 38674298, 2024). "Additionally, insights into the roles of PACAP and VIP in regulating testosterone production and testicular function could inform the development of novel therapeutic approaches for treating male infertility." (PMID 38674298, 2024).
mental disorder (1 paper, 2024). A disease that has its basis in the disruption of mental process. "Retinal vasoactive intestinal peptide amacrine cells (VIP-ACs) play an important role in various retinal light-mediated pathological processes related to different developmental ocular diseases and even mental disorders." (PMID 38315298, 2024).
metabolic acidosis (1 paper, 2021). "A prolonged (10h) VIP infusion (400 pmol/kg/h) has been shown to mimic the syndrome in healthy subjects who all developed watery diarrhea and metabolic acidosis." (PMID 33398457, 2021).
Miscarriage (1 paper, 2021). A pregnancy that ends at a stage in which the fetus is incapable of surviving on its own, defined as the spontaneous loss of a fetus before the 22th week of pregnancy. "Treatment with vasoactive intestinal peptide (VIP) in a miscarriage-prone mouse model (CBA/J×DBA/2) can regulate the endocytosis of maternal macrophages and promote the expression of TGF-β1 at the implantation site of the mouse, significantly increasing the number of implant points." (PMID 34531852, 2021).
multi-infarct dementia (1 paper, 2006). A common form of dementia caused by multiple cortical or subcortical cerebral infarctions. "Wikkelsö in 1985 examined the role of the vasoactive intestinal peptide (VIP) in the pathogenesis of NPH and in multi-infarct dementias." (PMID 17020616, 2006).
multiple endocrine neoplasia (1 paper, 2024). Multiple endocrine neoplasia (MEN) is a group of rare inherited cancer syndromes characterized by the development of two or more endocrine gland tumors, sometimes with tumor development in other tissues or organs. "Cases are sporadic, with no known association between familiar cancer syndromes, such as multiple endocrine neoplasia (MEN) syndromes, and VIP-producing neuroblastic tumors." (PMID 39328672, 2024).
necrotizing enterocolitis (1 paper, 2021). Necrotizing enterocolitis (NEC) is a devastating disease that affects mostly the intestine of premature infants. "VIP can have a good therapeutic effect on necrotizing enterocolitis by reducing the inflammatory response and the destruction of TJ proteins." (PMID 34899686, 2021).
neuroblastic tumor (1 paper, 2024). A group of nervous system tumors which display neuronal differentiation. "In the small intestine, however, it is a potent stimulator of electrolyte and water secretion and adenylate cyclase production, which explains the pathophysiology of refractory diarrhea in patients with VIP-producing neuroblastic tumors." (PMID 39328672, 2024).